MGMT (O-6-methylguanine-DNA methyltransferase)
Diseases named in the same sentence as MGMT in open-access papers (continued):
Sharing a sentence is not in itself a finding about the gene and the disease.
cancer (continued). "In addition, MGMT Leu84Phe variants may increase cancer risk in Caucasians and in the mixed ethnicities group, which suggests an appreciable difference among different ethnic populations." (PMID 24086516, 2013). "These interactions are crucial for understanding the role of MGMT in DNA repair and its implications in cancer biology." (PMID 41596413, 2026). "Collectively, these future-focused strategies aim to personalize therapy, reduce treatment failures, and improve overall survival rates for patients with MGMT-influenced cancers." (PMID 40895460, 2025). "The fact that we see the same results across three different cancer types, all characterized by frequent somatic MGMT methylation, at least provides indirect validation between cancer types." (PMID 39980037, 2025). "This comparative insight reinforces MGMT’s broad relevance while highlighting its context-dependent functional role in cancer biology and therapy optimization." (PMID 40895460, 2025). "The expression of MGMT is characteristically high in tumors and years ago emerged as a target for cancer therapy." (PMID 40001953, 2025). "GBM is a challenging cancer to treat due to several factors, including MGMT methylation status, ineffective penetration of treatment through the BBB, and the ability of GBM to evade cell death through DDR mechanisms." (PMID 39859189, 2025). "In agreement with this, we found that hypermethylation on the UBA1 promoter in cancer was rare, in contrast to the reported frequent hypermethylation on the MGMT promoter." (PMID 39540840, 2025). "Although MGMT is a key biomarker and therapeutic target in several cancers, converting lab insights into clinical success remains complex." (PMID 40895460, 2025). "The significance of MGMT status both at the expression and promoter methylation levels varies across cancer types, offering insights into its potential as a biomarker for diagnosis, prognosis, and therapeutic response." (PMID 40895460, 2025). "MGMT is a key DNA repair enzyme whose regulation has become a focal point for developing innovative therapies to tackle treatment resistance in cancers such as GBM." (PMID 40895460, 2025). "These cases highlight the translational potential of multi-omics approaches in personalizing MGMT-related cancer therapy." (PMID 40895460, 2025). "Ultimately, understanding MGMT’s dual role offers critical insights for personalized cancer therapy, especially in malignancies where alkylating agents remain a standard of care." (PMID 40895460, 2025). "Small molecules and RNA-based tools, including siRNAs and antisense oligonucleotides, have been used to reduce MGMT levels in cancer cells, enhancing TMZ sensitivity." (PMID 40895460, 2025). "Pharmacological or knockdown depletion of RBM39 led to a significant reduction in MGMT protein levels and increased sensitivity of cancer cells to TMZ." (PMID 41300971, 2025). "The overall response of cancer patients treated with TMZ is dependent on their MGMT activity, with patients conferring high activity being resistant to TMZ treatment." (PMID 39531065, 2025). "In this review, we take a comprehensive view of the intricate regulatory landscape surrounding MGMT in cancer, aiming to unravel its multifaceted biological and clinical relevance." (PMID 40895460, 2025). "The expression of MGMT is tightly regulated at multiple levels, which influences both cancer development and treatment response." (PMID 40895460, 2025). "Thanks to advances in multi-omics technologies, scientists are now able to paint a much clearer picture of MGMT’s role in cancer well beyond what single methylation tests can offer." (PMID 40895460, 2025). "Hypermethylation of genes such as O6-methylguanine-DNA methyltransferase (MGMT) and mutL homolog 1 (MLH1) impair DNA repair mechanisms, resulting in the accumulation of genetic mutations and cancer progression." (PMID 40718833, 2025).
cancer (continued). "Single-cell and spatial omics further unravel the intratumoral heterogeneity of MGMT expression and its epigenetic determinants across cancer types." (PMID 40895460, 2025). "The implications of MGMT (DR) modulation through the Wnt/β-catenin pathway for cancer treatment, particularly GBM, and different compounds have demonstrated anti-tumor activity reversing the resistance to TMZ." (PMID 40001953, 2025). "It has been reported that activation of the canonical Wnt/β-catenin pathway induces MGMT expression, and inhibition of Wnt signaling augments the effects of alkylating drugs, restoring sensitivity in different cancers." (PMID 40001953, 2025). "MGMT’s repair work is vital for normal cellular processes, and its functionality, by enabling direct reversal of alkylation, can lead cancer cells to develop resistance to chemotherapeutic alkylators." (PMID 40183077, 2025). "Anomalous methylation of p16, DAPK1, and MGMT tumour suppressor genes has been detected in OSCC tissues and linked to early cancer development." (PMID 40027232, 2025). "The efficacy of drugs like temozolomide in cancers with hypermethylated O6-Methylguanine-DNA-methyltransferase (MGMT) promoters demonstrates the therapeutic potential of targeting these epigenetic changes." (PMID 40016470, 2025). "Pharmacological depletion or siRNA-mediated knockdown of RBM39 led to a marked reduction in MGMT protein levels in MGMT-expressing cancer cells." (PMID 41300971, 2025). "Ultimately, understanding and modulating MGMT represents a cornerstone of future efforts to deliver more precise, effective, and individualized cancer care." (PMID 40895460, 2025). "The study is statistically well powered to detect a potential increase in HR of each individual cancer, both in respect of MGMT epimutations and rs16906252 status." (PMID 39980037, 2025). "Recent research has highlighted the significant role of CDK20 (cyclin-dependent kinase 20) and MGMT (O6-methylguanine-DNA-methyltransferase) in the development and treatment of various cancers." (PMID 39767561, 2024). "This augmentation in median survival from 12.1 to 14.6 months was particularly beneficial to patients with methylation at the O6-methylguanine-DNA methyltransferase (MGMT) promoter in cancer DNA." (PMID 39201386, 2024). "When cancer cells exhibit high levels of MGMT, they can repair the damage induced by alkylating chemotherapy agents effectively, such as TMZ, leading to drug resistance." (PMID 38672496, 2024). "Both in vitro and in vivo studies indicate that cancer cells with MGMT expression exhibit a pronounced response to the combined administration of temozolomide and PARPi." (PMID 39055560, 2024). "Another avenue of research involves the deployment of MGMT inhibitors, which have the potential to sensitize cancer cells to the cytotoxic effects of agents such as temozolomide and dacarbazine." (PMID 39055560, 2024). "It becomes increasingly apparent that elucidating the complex functions and regulatory pathways of MGMT is key to the development of more sophisticated and precise cancer therapies." (PMID 39055560, 2024). "The quantification of MGMT levels holds considerable prognostic value for anticipating the therapeutic efficacy of alkylating agents, thereby rendering MGMT assessment an integral aspect of the treatment planning process for certain cancers." (PMID 39055560, 2024). "MGMT was shown to play a major role in conferring cancer resistance to BCNU and other alkylating agents." (PMID 38892179, 2024). "These GBMs belonged to a cluster of cancers treated with TMZ or lomustine or both and presented mutations in the DNA mismatch repair system and heavy methylation of O-6-methylguanine-DNA methyltransferase (MGMT) promoter." (PMID 39595195, 2024). "O6-methylguanine-DNA methyltransferase (MGMT) stands out as one of the first DNA methylation cancer biomarkers." (PMID 39149674, 2024).
cancer (continued). "The potential to tailor treatments based on the MGMT status of tumors offers a promising avenue for increasing the specificity and potency of cancer therapies, thereby improving the prognosis and quality of life for patients afflicted with this disease." (PMID 39055560, 2024). "The objective of this approach is to prevent MGMT inhibition in normal tissues while sensitizing cancer cells to chemotherapy." (PMID 38254819, 2024). "It has also been shown that hINF alpha 2b produced in plant systems reduced the level of the repair enzyme MGMT in Hep-2 cancer cells, thereby increasing the sensitivity of cancer cells to chemotherapy." (PMID 38393430, 2024). "Apart from being an avenue for cancer therapeutic strategies, MGMT has also been investigated as a valuable research tool for the specific labeling of proteins." (PMID 38254819, 2024). "Overall, our findings suggest a possible link between BRCA1 and MGMT epimutations and the occurrence of cancer in the family." (PMID 38542081, 2024). "O6‐methylguanine‐DNA methyltransferase (MGMT) is a DNA repair enzyme that removes alkyl groups from the O6 position of guanine in DNA, and its activity is critical in the resistance of cancer cells to alkylating agents." (PMID 39618336, 2024). "The exploration of MGMT methylation across various cancer types underscores its potential as a biomarker for predicting treatment response and tailoring therapeutic approaches." (PMID 39055560, 2024). "This research highlights the critical need for further investigation into the specific mechanisms by which CDK20 and MGMT influence cancer development and treatment to optimize therapeutic strategies and improve patient outcomes." (PMID 39767561, 2024). "In light of this, the conjugation of a glucose group to the MGMT inhibitor represents a promising concept for the development of cancer-selective MGMT inhibitors." (PMID 38254819, 2024). "Furthermore, it has been demonstrated that the gene O6-methylguanine methyltransferase (MGMT), encoding for a DNA repair enzyme that is responsible for the removal of alkylation adducts on DNA, is frequently hypermethylated in several types of cancer, including glioma and colorectal cancer." (PMID 39056791, 2024). "Liu and Gerson highlighted the clinical implications of MGMT modulation, emphasizing its potential to improve responses to alkylating agents in cancer therapy." (PMID 39055560, 2024). "Researchers explore alternative strategies like cancer-selective inhibitors, MGMT expression downregulation, autoantibodies, and localized drug delivery to attenuate MGMT activity and minimize normal cell exposure." (PMID 38254819, 2024). "Specifically, TMZ treatment was performed in patients whose cancers displayed silencing of O6-methylguanine-DNA methyltransferase (MGMT), which is a DNA repair enzyme with a key role in chemoresistance to O6-alkylating agents such as TMZ." (PMID 39271762, 2024). "Ectopic MEN1 expression downregulated MGMT expression and re‐sensitized cancer cells to TMZ by suppressing the nuclear accumulation and transcriptional activity of β‐Catenin." (PMID 39041891, 2024). "MGMT promoter hypermethylation results in the suppression of its expression and to its inactivation, leading to an increased sensitivity of cancer cells to alkylating agents like temozolomide (TMZ)." (PMID 39618336, 2024). "It has been demonstrated that many cancer cell lines develop resistance to TMZ due to varying levels of expression of O6-methylguanine-DNA-methyltransferase (MGMT)." (PMID 39409913, 2024). "Epigenetic regulation through the methylation of the MGMT gene promoter prevents protein synthesis in cancer cells, consequently increasing their sensitivity to alkylating agents." (PMID 39594133, 2024). "MEN1 deficiency induced the nuclear accumulation of β‐Catenin and the recruitment of β‐Catenin to the MGMT promoter, which promotes MGMT transcription and leads to cancer cell growth and disruption of the TMZ response." (PMID 39041891, 2024).
cancer (continued). "The elevated expression of the MGMT gene decreased drug sensitivity, while the inhibition of MGMT resulted in an enhanced sensitivity of cancer cells to topo-active drugs." (PMID 38398072, 2024). "Understanding the methylation status of the MGMT gene can, therefore, provide valuable prognostic information and guide the selection of therapeutic strategies in the treatment of various cancers." (PMID 39055560, 2024). "Considering the methylation of MGMT, advanced-stage cancer specimens were found to have a significantly higher level of methylation compared to early stages and non-malignant CRC in the present study." (PMID 37510370, 2023). "The therapeutic effects of alkylating drugs are, therefore, blunted by high levels of MGMT activity in cancer cells, which can be a key factor in treatment failure." (PMID 37901797, 2023). "MGMT blocking is employed for adjuvant chemotherapy in malignancies that depend on the rate of MGMT re-synthesis in the cancer cells." (PMID 37373325, 2023). "MGMT existence in normal cells is important for their protection, but when present in cancer cells it counter-acts the anti-cancer activity of the alkylating agents, conferring resistance in MGMT promoter unmethylated and partially methylated cells." (PMID 37131108, 2023). "On the other hand, the disulfide compounds disulfiram and α-lipoic acid were identified as direct MGMT inhibitors that trigger MGMT depletion in cancer cells." (PMID 36902118, 2023). "Despite the necessity of more studies, we reported a proof of concept to use MGMT inhibitors, the available adjunctive anti-cancer drugs, to attenuate sepsis-induced hyper-inflammation." (PMID 37373325, 2023). "Given that MGMT is not a known repressor of gene expression, it is possible that the suppression of TUSC3 promoter activation in MGMT-UM GSCs occurs through a complex or machinery mediated by MGMT, which suggests a novel role of MGMT in cancers." (PMID 37894860, 2023). "The heavy dependence of cancer cells on MGMT-mediated DNA repair makes the regulation of MGMT expression an attractive target for cancer therapy." (PMID 38071213, 2023). "In our experiments, CSCs show higher MGMT expression along with significant elevation of cancer stemness marker NANOGP8 as compared to GBM." (PMID 36834653, 2023). "MGMT is known to repair alkylating agent damage to malignant tumors and inhibit the effects of alkylating agents." (PMID 37161026, 2023). "It has also been shown that MGMT is active in the development, progression, and diagnosis of cancer." (PMID 37834832, 2023). "MGMT is important for the DSB repair process, with decreased MGMT function linked to increased cancer risk." (PMID 35955487, 2022). "Molecular mechanisms including downregulation of MGMT and PD-L1, and killing cancer stem cells utilizing BP, are reported in this study." (PMID 35205800, 2022). "For this boost a high dose (200 mg/m2/day), which is usually used for maintenance therapy, is recommended since it is expected to be effective also in cancer cells expressing MGMT at a very low level." (PMID 35785203, 2022). "In general, cancer tissues exhibit increased MGMT activity compared to that of normal tissues, however, concordance between MGMT activity and clinical outcomes in HSCT setting remains to be determined." (PMID 34711928, 2022). "Apparently, this is an obstacle to the subsequent DNA replication in S phase, and finally, it will cause DNA DSB in MGMT- and MMR+ cancer cells." (PMID 35281059, 2022). "MGMT is a DNA repair protein that functions during DNA damage by alkylating agents and plays a role in conferring resistance to cancer cells against some cancer chemotherapies." (PMID 35115604, 2022). "XAF1 expression is associated with overall survival of TMZ treatment patients, particularly with low MGMT cancer." (PMID 35274103, 2022).
cancer (continued). "In this study, radiomics features extracted from multimodal images of GBM patients with annotated MGMT methylation status were downloaded from The Cancer Imaging Archive (TCIA) public database for retrospective analysis." (PMID 35927323, 2022). "We further used the CGGA-LGG database to compare the difference in FCGR3A mRNA expression in groups divided by age, gender, cancer type, WHO grade, 1p19q codel, IDH1-mutation, MGMT methylated, radiotherapy treatment, and chemotherapy treatment." (PMID 39280892, 2022). "In vitro, radiation-enhanced AMONs delivery decreased MGMT protein and significantly reduced human cancer cell proliferation index and cell viability in conjunction with temozolomide treatment." (PMID 33850305, 2022). "In these malignant tumors, pseudoprogression commonly occurs in the first 12 weeks following chemoradiation with temozolomide, especially when MGMT promotor methylation is present and generally indicates a more favorable prognosis." (PMID 35326697, 2022). "DNA methylation can also be used for specific biomarkers and cancer-relevant promoters such as MGMT promoter methylation status and MLH1 status, respectively." (PMID 35527288, 2022). "Regulation of O6-MeG DNA methyltransferase (MGMT) and an absence of DNA mismatch repair (MMR) are now widely recognized as the most important factors contributing to TMZ resistance in gliomas." (PMID 36437944, 2022). "The prevalence of MGMT promoter hypermethylation in the Italian cohort was 18%, which is clinically relevant in these rare cancers." (PMID 35621918, 2022). "Methylation of the MGMT promoter can silence the gene in cancer cells and limit their ability to repair DNA, rendering cancer cells more vulnerable to TMZ." (PMID 35565282, 2022). "Both cancer cell lines are traditionally resistant to alkylating agents potentially due to high levels of MGMT protein expression." (PMID 33850305, 2022). "Heatmap showed that the two groups had distinct patterns of clinical traits, like cancer type, grade, subtype, MGMT, 1p19q, IDH, and age." (PMID 36070228, 2022). "Multiple studies have revealed that MGMT plays a vitally important role in the mechanism of resistance to alkylating agents such as TMZ, and cancers with low level of MGMT expression are more tend to have a better response to TMZ." (PMID 36483042, 2022). "In animal models, increasing MGMT levels is to guard against the event of tumors including carcinoma." (PMID 35933451, 2022). "Group TT of rs12268840 had the highest rate of second primary carcinoma (30.4%, p = 0.0003), lowest expression of MGMT based on cis-eQTL analysis in normal gastroesophageal tissue (p = 1.99 × 10−17), and worst oncologic outcome." (PMID 34529172, 2022). "Nevertheless, MGMT inhibitors appear to be mandatory in MGMT-expressing tumors for DIX-dependent cancer therapeutic approaches in which TMZ or dacarbazine are applied to induce cancer cell immunogenicity." (PMID 34639014, 2021). "MGMT is considered a perspective target in cancer therapy because of its important role in the protection of genomic damage from alkylating agents." (PMID 33397362, 2021). "Accumulating evidence is indicating that high MGMT expression levels can predict worse survival in patients with various types of cancers treated with platinum-based chemotherapy regimens." (PMID 33397362, 2021). "Pyrvinium pamoate (PP), the FDA-approved anthelminthic drug, has been reported to inhibit the Wnt/β-catenin pathway within numerous cancer types, and Wnt/β-catenin signaling pathway can modulate the expression of MGMT gene." (PMID 34642308, 2021). "The activity of MGMT is regulated by its promoter and its hypermethylation leads to gene silencing in cancer." (PMID 34638292, 2021). "The mifepristone/temozolomide combination produced a sharply lower expression of VEGF, CD31, P-gp, and MGMT compared to the other groups with implanted cancer cells, including the untreated animals and those given mifepristone or temozolomide alone." (PMID 33123485, 2020).